BRCA1 (BRCA1 DNA repair associated)
Diseases named in the same sentence as BRCA1 in open-access papers (continued):
Sharing a sentence is not in itself a finding about the gene and the disease.
breast cancer (continued). "Low BRCA1 protein and mRNA expression has also been associated with improved survival in breast cancer and non-small cell lung cancer." (PMID 21854619, 2011). "Mutations in two genes that were initially identified as predisposing carriers to early-onset breast cancer, BRCA1 and BRCA2, cause similar perturbations in cellular responses to DNA damage but predispose carriers to distinct tumor types." (PMID 22110403, 2011). "The 15-year actuarial risk of contralateral breast cancer was 36.1% for women with a BRCA1 mutation and was 28.5% for women with a BRCA2 mutation." (PMID 21487411, 2011). "It is estimated that a BRCA1/2 mutation is found in 2–6% of breast cancer patients and 10–15% of epithelial ovarian cancer patients." (PMID 22312502, 2011). "There is insufficient evidence at this time to forgo surveillance and breast conservation as viable options for BRCA1/2 mutation carriers, options offered to patients with most other forms of breast cancer." (PMID 22295226, 2011). "In this model, the mammary tumours that spontaneously develop mimic key features of human breast cancer-(BRCA1)-associated mammary carcinomas." (PMID 22332018, 2011). "Then, it seems that hereditary breast cancer is associated with short telomeres, especially in BRCA1 and BRCA2 mutation carriers, as well as in a subgroup of BRCAX." (PMID 21829373, 2011). "In preclinical models of BRCA1-deficient breast cancers, there is an increased susceptibility to DNA-damaging agents, particularly those able to induce double-strand breaks such as cisplatin or carboplatin." (PMID 22312556, 2011). "The subsequent phase II study in 27 breast cancer patients with BRCA mutation (18 BRCA1 deficient and 9 BRCA2 deficient) showed RR of 41% and median PFS of 5.7 months." (PMID 21504625, 2011). "The risk of developing breast cancer by the age of 70 for carriers of BRCA1 is 57% to 65%, while the risk in BRCA2 carriers is slightly lower, at 45% to 49%, based on the findings of two recent metaanalyses." (PMID 22295226, 2011). "Women who carry a germline mutation in either the BRCA1 or the BRCA2 gene face a high lifetime risk of breast cancer and, once diagnosed with breast cancer, face a high risk of second primary cancer in the contralateral breast." (PMID 21487411, 2011). "Family history of breast and ovarian cancer, besides breast cancer bilaterality, early-onset breast cancer and ethnicity, constitute the basic criteria for identifying cases affected by BRCA1 or BRCA2 mutations." (PMID 21989022, 2011). "It has been estimated that tamoxifen reduces breast cancer risk in BRCA1-mutation carriers by 13% and in BRCA2-mutation carriers by 27%." (PMID 22312502, 2011). "One study examined the effects of a Rad51 genotypes in BRCA1/2 carriers and reported that Rad51 135G>C genotype association with breast cancer risk was greater in BRCA1 carriers with truncating mutations (i.e. 185delAG)." (PMID 21708019, 2011). "In breast cancer patients of Jewish origin, the BRCA1 mutation rate is increased at 10% compared to the general breast cancer population." (PMID 22312502, 2011). "Veliparib potentiated inhibitory effect of cisplatin, carboplatin and cyclophosphamide towards human BRCA1-mutated breast cancer xenografts (MX-1) growing in immunocompromised mice." (PMID 21819606, 2011). "Many women with a BRCA1/2 mutation opt for mastectomy instead of breast-conserving measures at the time of a breast cancer diagnosis." (PMID 22295226, 2011). "In order to gain insights into the downstream factors involved in human BRCA1-associated breast cancers, a mouse model was developed with a conditional Brca1 gene deletion." (PMID 21888628, 2011).
breast cancer (continued). "On the other hands, the majority of BRCA1-associated breast cancers is TN and expresses basal cytokeratins." (PMID 21496280, 2011). "Some risk is conferred by rare variants with large effects, such as the BRCA1/BRCA2 mutations that increase breast cancer susceptibility." (PMID 21244661, 2011). "A significant proportion of individuals with hereditary breast cancer have mutations in the tumor suppressor genes BRCA1 (OMIM # 113705) and BRCA2 (OMIM # 600185)." (PMID 22185575, 2011). "Mastectomy has long been proposed as a means of avoiding breast cancer in women with BRCA1 and BRCA2 mutations." (PMID 22312537, 2011). "Here, we explore the relationships between the MSA and the Rad51 gene, which encodes a DNA repair enzyme that interacts with BRCA1 and BRCA2, in BRCA1 mutation carriers and women with sporadic breast cancer." (PMID 21708019, 2011). "The woman with the BRCA1 del1A-23 mutation had breast cancer diagnosed at the age of 33 years and a paternal grandmother with breast cancer diagnosed at age 71 years (verified)." (PMID 21343941, 2011). "Since BRCA1 mutations predispose to breast cancer at an earlier age, it would be more difficult to have large differences between generations in BRCA1 families." (PMID 21829373, 2011). "This mouse model demonstrates a pattern of progressive adenocarcinoma with similar genetic changes and pathophysiology as seen in human breast cancers associated with BRCA1-mutations." (PMID 21888628, 2011). "It has been estimated that between 5% and 10% of women diagnosed with breast cancer have a hereditary form of the disease, primarily caused by a BRCA1 or BRCA2 gene mutation." (PMID 21219598, 2011). "Breast cancer diagnosis was significantly associated with the MSA among women from BRCA1 families (OR = 3.2 95%CI: 1.5-6.7; p = 0.004)." (PMID 21708019, 2011). "It has been reported that only 5.5% of women with a BRCA1 or BRCA2 mutation have used tamoxifen to reduce their breast cancer risk." (PMID 22312502, 2011). "Inheritance of a mutation in either BRCA1 or BRCA2 accounts for approximately 5% of all breast cancer cases, but varies by country." (PMID 22085629, 2011). "As aCGH is a rather complex method, we translated the BRCA1aCGH profile to a Multiplex Ligation-dependent Probe Amplification (MLPA) assay, to identify both BRCA1-mutated breast cancers and sporadic cases with a BRCA1-likeaCGH profile." (PMID 22032731, 2011). "Their latest study, published in 2010, compares breast conservation to mastectomy in 655 women with BRCA1/2 mutations diagnosed with breast cancer." (PMID 22295226, 2011). "In this study, we used both single-end and paired-end sequencing strategies to discover gene fusions in breast cancer transcriptomes with BRCA1 mutations." (PMID 22032724, 2011). "The cumulative breast cancer risk for BRCA1 and BRCA2 mutation carriers at the age of 70 was, in different studies, reported to be between 36% and up to 71%." (PMID 21232165, 2011). "Previous analysis of candidate genomic regions using a linkage approach suggested specific modification of breast cancer risk among BRCA1 mutation carriers by common genetic variation at chromosome 5q33-34." (PMID 22110403, 2011). "The study was initiated to determine the modification of breast cancer risk associated with hormone use by a subset of genes involved in hormone metabolism and cell cycle regulation, of which BRCA1 is included." (PMID 22312502, 2011). "Many BRCA1/2 mutation carriers diagnosed with breast cancer (affected carriers) opt for bilateral mastectomy rather than BCT for initial treatment of disease." (PMID 22295226, 2011). "While studies have identified low-penetrance alleles that associate with breast cancer risk in carriers of BRCA1 mutations and carriers of BRCA2 mutations, specificities have also been detected." (PMID 22110403, 2011).
breast cancer (continued). "Previous studies have demonstrated that common breast cancer susceptibility alleles are differentially associated with breast cancer risk for BRCA1 and/or BRCA2 mutation carriers." (PMID 22053997, 2011). "Molecular analysis of BRCA1 founder mutations among 2546 unselected breast cancer patients has revealed the presence of mutations in 96 (3.77%) cases, including 25 (0.98%) c.4034delA mutations and 69 (2.70%) c.5266dupC mutations." (PMID 22032251, 2011). "BRCA1 is an important susceptibility gene for breast cancer that increases the lifetime risk of breast cancer, particularly in the pre-menopausal age group." (PMID 23508738, 2011). "In these British and American studies, between one-half and two-thirds of the breast cancer patients carrying a BRCA1 or BRCA2 mutation opted for a bilateral mastectomy, with some opting for a delayed CPM instead of direct BLM." (PMID 21219598, 2011). "Mutations to the BRCA1 gene are associated with a significant increase in the risk of breast cancer." (PMID 21816114, 2011). "In fact, we and others have shown that sporadic basal-like breast cancers resemble BRCA1 mutated cancers in many different ways." (PMID 22032731, 2011). "Clinical evidence is emerging that BRCA1- associated breast cancers are particularly sensitive to platinum agents." (PMID 21771338, 2011). "In the clinical setting, BRCA1-linked breast cancers are more often of the “triple negative” basal type than are either sporadic or BRCA2-linked breast cancers, for reasons that are not well understood." (PMID 21779182, 2011). "Preliminary evidence trended towards an increased risk in postmenopausal breast cancer in BRCA1 minor allele carriers on estrogen hormone therapy compared to those with the major BRCA1 allele genotype." (PMID 22312502, 2011). "Of these, 39 (29%) have now been found to carry a germline mutation in a breast cancer susceptibility gene, 34 (26%) in BRCA1." (PMID 21281505, 2011). "Germline mutations in BRCA1 have been detected in approximately half of human familial breast cancer cases." (PMID 21888628, 2011). "Breast cancer risks for BRCA1 and BRCA2 mutation carriers have been estimated to range between 40 and 87% by age 70 with population-based estimates tending to be lower than estimates based on families with multiple affected individuals." (PMID 22053997, 2011). "Germline mutations in BRCA1 are relatively rare in sporadic forms of breast cancer although deregulation in BRCA1 expression is common." (PMID 21914189, 2011). "Mutations in BRCA1 are associated with an increased risk for breast cancer (up to 80% lifetime risk) and ovarian cancer (up to 50%)." (PMID 22032724, 2011). "For women with a BRCA1 mutation, oophorectomy was associated with a significant reduction in the risk of contralateral breast cancer in BRCA1 carriers (RR 0.48; 95% CI 0.27–0.84; P=0.01)." (PMID 21487411, 2011). "Two subsequent Phase II studies evaluating olaparib in previously treated BRCA1/2-mutated breast cancer and ovarian cancer patients were recently reported." (PMID 21504625, 2011). "We used Illumina sequencing technology to sequence the transcriptomes of five BRCA1-mutated breast cancer cell lines, three BRCA1-mutated primary tumors, two secretory breast cancer primary tumors and one non-tumorigenic breast epithelial cell line." (PMID 22032724, 2011). "Our investigation of several BRCA1-mutated breast cancer cell lines and primary tumors revealed three previously uncharacterized non-recurrent gene fusions, two in cell lines and one in a primary tumor." (PMID 22032724, 2011).
breast cancer (continued). "More recently, a number of preclinical studies examining the activity of platinum agents in the treatment of TN and BRCA1-associated breast cancers have demonstrated increased sensitivity to these agents." (PMID 22312556, 2011). "This is the first report to investigate the associations between 12 common breast cancer susceptibility alleles and ER and PR status of breast tumours in BRCA1 and BRCA2 mutation carriers." (PMID 22053997, 2011). "Cisplatin induced almost complete growth inhibition of HCC1937-derived (BRCA1-mutated) breast cancer xenografts, while BRCA1-reconsituted HCC1937 xenografted tumors showed only partial response to cisplatin treatment." (PMID 21819606, 2011). "A total of 127 breast cancer patients were tested for BRCA1 and BRCA2 mutations using a combination of laboratory techniques." (PMID 22085629, 2011). "About 5-10% of all breast cancers are estimated to be hereditary, and germline mutations in the tumor-suppressor genes BRCA1 (MIM#113705) and BRCA2 (MIM#600185) are found in a proportion of this group." (PMID 21989022, 2011). "Three previously reported breast cancer-associated variants, BRCA1 c.5095C > T, CHEK2 c.470T > C, and CHEK2 c.1100delC, were observed in eleven (13.4%) individuals." (PMID 21356067, 2011). "We have recently reported that a family history of cancer influences breast cancer risk in women with a BRCA1 or BRCA2 mutation." (PMID 21487411, 2011). "Many of the genes already associated with breast cancer susceptibility encode proteins that operate together with BRCA1 and BRCA2 in the DNA damage response pathway (DDR)." (PMID 21774837, 2011). "Knowing that a woman with breast cancer carries a germline BRCA1 mutation informs her clinical management and that of her relatives." (PMID 21281505, 2011). "We applied two criteria (one for family history and one for tumour morphological features) to select women participating in the Breast Cancer Family Registry (BCFR) who had already undergone extensive BRCA1 mutation screening." (PMID 21281505, 2011). "The NCCN recommends that breast cancer screening for BRCA1- and BRCA2-mutation carriers should include annual mammography and clinical breast examination every 6–12 months, starting at age 25 or individualized based on one's family history." (PMID 22312502, 2011). "The sample sizes for tumour subtypes, while still large, were, therefore, much smaller than were available for analyses of breast cancer risk overall, particularly for ER-positive breast cancer in BRCA1 carriers and ER-negative breast cancer in BRCA2 carriers." (PMID 22053997, 2011). "Our studies suggest that the window of opportunity for effective breast cancer prevention using EGFR inhibitors is a state at which loss of BRCA1 and gain of EGFR have occurred, but the growth factor independence of cancer cells has not yet been established." (PMID 21396117, 2011). "This study is evaluating the behavioral and psychosocial effects of the routine offer of RGCT to newly diagnosed primary breast cancer patients who meet criteria for being at-risk of having a BRCA1 or BRCA2 gene mutation." (PMID 21219598, 2011). "Specific morphological characteristics of breast cancers are predictive of the presence of mutations in BRCA1 and BRCA2 which predispose to breast and ovarian cancers, particularly if they occur in women before the age of 40 years." (PMID 21352566, 2011). "Genetic testing of these women identified 60 (32%) with a mutation in a breast cancer susceptibility gene, 34 (18%) in BRCA1." (PMID 21281505, 2011). "Our group has previously employed array Comparative Genomic Hybridization (aCGH) to assess the genomic patterns of BRCA1-mutated breast cancers." (PMID 22032731, 2011). "The objective of this study was to estimate the risk of contralateral breast cancer in BRCA1 and BRCA2 carriers; and measure the extent to which host, family history, and cancer treatment-related factors modify the risk." (PMID 21487411, 2011).
breast cancer (continued). "Loss of BRCA1 function plays a role in the development of a substantial number of breast cancers, including more than 50% of hereditary cases due to germline mutations and up to 30% of sporadic cases through mechanisms of epigenetic silencing." (PMID 21771338, 2011). "The general pattern of associations with PR-positive and PR-negative breast cancer for BRCA1 mutation carriers was similar to that seen for ER status." (PMID 22053997, 2011). "In conclusion, the fact that methylation of the BRCA1 gene in PB DNA correlates with increased risk of breast cancer, allows to anticipate that aberrant methylation of genes in PB and disease predisposition are linked." (PMID 22129206, 2011). "The multivariate odds ratio for contralateral breast cancer associated with tamoxifen use was 0.50 for carriers of BRCA1 mutations (95% CI, 0.30–0.85) and 0.42 for carriers of BRCA2 mutations (95% CI, 0.17–1.02)." (PMID 22312502, 2011). "To complement the linkage approach, we evaluated the effect of common HMMR genetic variation on breast cancer risk in BRCA1 and BRCA2 mutation carriers." (PMID 22110403, 2011). "BRCA1/2 mutation carriers are known to have an increased incidence of breast cancer and premalignant lesions." (PMID 22295226, 2011). "Breast cancer patients who carry a BRCA1/2 mutation have a 3% annual risk of developing contralateral breast cancer, with the overall risk being as high as 52% by the age of 70." (PMID 21219598, 2011). "This work has also identified a fascinating group of early-onset breast cancers that share the morphological features of early-onset breast cancers that carry identifiable BRCA1 mutations." (PMID 21343941, 2011). "Taken together, our data suggest a novel targeted approach to treating BRCA1-mutated or other DNA repair-deficient breast cancers to include gemcitabine and cisplatin." (PMID 21771338, 2011). "It is clear that women with BRCA1/2 mutations have a much higher risk of developing breast cancer than the 12.5% lifetime risk of the general population." (PMID 22295226, 2011). "The CIMBA has assessed risk in BRCA1/2 carriers for various SNPs in genes that had been previously found to be associated with increased breast cancer risk in the general population, mostly via genome-wide association studies." (PMID 21427728, 2011). "There was a clear inverse correlation between the intensity of CD44 expression and BRCA1 nuclear expression in this series of breast cancers, indicating that higher expression of BRCA1 was associated with lower CD44 expression (p=0.04)." (PMID 23508738, 2011). "A recent meta-analysis was published of eight studies that estimated the risk of first primary breast cancer in BRCA1/2 mutation carriers who were treated with prophylactic oophorectomy relative to carriers who had intact ovaries." (PMID 21487411, 2011). "Knowing a young woman with newly diagnosed breast cancer has a germline BRCA1 mutation informs her clinical management and that of her relatives." (PMID 21343941, 2011). "Selecting women affected with breast cancer who are most likely to carry a germline mutation in BRCA1 and applying the most appropriate test methodology remains challenging for cancer genetics services." (PMID 21281505, 2011). "Current estimates indicate that women who carry mutations in the BRCA1 or BRCA2 genes have up to an 85% lifetime risk of developing breast cancer, and can also have up to a 60% lifetime risk of developing ovarian cancer." (PMID 21219598, 2011).